P4HA2 (prolyl 4-hydroxylase subunit alpha 2)
Description:
Catalyzes the post-translational formation of 4-hydroxyproline in -Xaa-Pro-Gly-sequences in collagens and other proteins.
Synonyms: C-P4Halpha(II); lncRNA-PE; MYP25
Tractability: Small molecule: a structure with a bound ligand is known. Antibody: UniProt predicts a signal peptide or a membrane-spanning region. PROTAC: ubiquitination databases record sites on it; its protein half-life has been measured.
Target class: Enzyme; Oxidoreductase
Gene: Protein-coding gene on chromosome 5 (132,190,094 to 132,295,315, reverse strand). Ensembl gene ENSG00000072682.
Subcellular location: Endoplasmic reticulum lumen
Subcellular location (Human Protein Atlas): Endoplasmic reticulum; Vesicles
Pathways (Reactome):
Disease: Maturation of DENV proteins
Extracellular matrix organization: Collagen biosynthesis and modifying enzymes
Gene Ontology:
Molecular function: procollagen-proline 4-dioxygenase activity; protein binding; electron transfer activity; iron ion binding; L-ascorbic acid binding; oxidoreductase activity, acting on paired donors, with incorporation or reduction of molecular oxygen
Cellular component: endoplasmic reticulum; endoplasmic reticulum lumen; procollagen-proline 4-dioxygenase complex
Genetic constraint (gnomAD): Loss-of-function variants: 29 observed, 47.02 expected, observed/expected ratio (o/e) 0.62, 90% interval 0.46 to 0.84. The upper end of that interval is the gene's LOEUF score, 0.84, which puts it in group 3 of 6, group 1 being the genes least tolerant of losing a copy. Missense variants: 448 observed, 531 expected, observed/expected ratio (o/e) 0.84, 90% interval 0.78 to 0.91. Synonymous variants: 179 observed, 206.85 expected, observed/expected ratio (o/e) 0.87, 90% interval 0.76 to 0.98.
Homologues: Orthologues: chimpanzee P4HA2 (98% identical), macaque P4HA2 (97% identical), pig P4HA2 (93% identical), rabbit P4HA2 (92% identical), guinea pig P4HA2 (91% identical), rat P4ha2 (91% identical), mouse P4ha2 (91% identical), dog P4HA2 (90% identical), tropical clawed frog p4ha2 (72% identical), zebrafish p4ha2 (69% identical), Drosophila melanogaster CG31021 (20% identical), Caenorhabditis elegans phy-3 (12% identical), and 2 more. Paralogues in human: P4HA1 (59% identical), P4HA3 (37% identical), P4HTM (16% identical).
Diseases named in the same sentence as P4HA2 in open-access papers:
P4HA2 is named in the same sentence as 72 diseases in open-access papers, as found by Europe PMC text mining. Sharing a sentence is not in itself a finding about the gene and the disease. The quoted sentences say what the papers report.
breast carcinoma (30 papers, 2014 to 2026). "It has been demonstrated that P4HA2, which has an association with a poor prognosis, enhances breast cancer growth and metastasis by controlling collagen deposition." (PMID 38777998, 2024). "Consistent with our findings, studies demonstrated that high P4HA2 expression was associated with poor survival in breast cancer." (PMID 36998462, 2023). "High P4HA2 expression is associated with poor prognosis in some malignant tumors, such as breast cancer, cervical cancer, and prostate cancer." (PMID 36403427, 2022). "Analysis using the Breast Cancer Gene-Expression Miner v4.1(bc-GenExMiner v4.1) database showed that high P4HA2 mRNA is associated with higher metastatic relapse and/or death (p < 0.0001)." (PMID 30410060, 2018). "Using gene co-expression analysis, we showed that P4HA2 was associated with expression of Col1A1, Col3A1, and Col4A1 during breast cancer development and progression." (PMID 24383403, 2014). "Furthermore, high levels of P4HA2 has been associated with decreased survival in a breast cancer dataset with almost 2000 patients, and is an independent predictor of disease outcome with respect to standard clinopathological parameters." (PMID 32500033, 2020). "COL3A1 has also been reported in other cancer types such as breast and colorectal cancers, with an association between COL3A1 and P4HA2 with poor prognosis in breast cancer, and correlation between elevated epithelial COL3A1 protein expression and unfavorable outcome in colorectal cancer." (PMID 31533654, 2019). "Here, we showed that expression of P4HA2 and collagen genes (Col1A1, Col3A1, and Col4A1) is significantly correlated during breast cancer development and progression, and that increased mRNA levels of P4HA2 are associated with poor prognosis in breast cancer patients." (PMID 24383403, 2014). "Laboratory experiments confirmed that silencing P4HA2 suppressed proliferation and migration abilities of breast cancer cells." (PMID 41424847, 2026). "Interventions targeting P4HA2 are expected to provide a novel strategy for breast cancer treatment, particularly holding significant translational value for cases with radiotherapy resistance." (PMID 41424847, 2026). "In the ieu-a-1126 cohort, genes with causal relationships to breast cancer included GNB2, HADH, OAS2, OCIAD2, P4HA2, and PAFAH1B3." (PMID 41424847, 2026). "Across breast cancer subtypes, P4HA2 expression varied significantly, with highest expression in HER2 subtype and lowest in Normal-like subtype." (PMID 41424847, 2026). "In the ebi-a-GCST90018799 cohort, genes with causal relationships to breast cancer included NOP58, OCIAD2, P4HA2, PEMT, and PNPLA2." (PMID 41424847, 2026). "Subsequently, we further explored the effects of radiotherapy and P4HA2 on breast cancer cells through experimental validation." (PMID 41424847, 2026). "Through various analytical approaches, the expression of P4HA2 was found to be significantly elevated in breast cancer, correlating closely with tumor stage, grade, and patient prognosis." (PMID 41424847, 2026). "Increased expression of P4HA2 has been detected in breast cancer, oral squamous cell carcinoma, papillary thyroid carcinoma, lung adenocarcinoma, B lymphoma, and glioma." (PMID 40406250, 2025). "A previous study has reported that P4HA2 enhances breast cancer progression and metastasis through collagen deposition regulation." (PMID 39764560, 2025). "Conversely, depletion of P4HA2 inhibited breast cancer cell proliferation and invasiveness in vitro and in vivo, by reducing collagen deposition." (PMID 40454316, 2025). "Lastly, analysis of grossly uninvolved tissues (lung and liver) collected from the rapid autopsy of a HER2+ breast cancer patient revealed that DTCs are positive for P4HA2 (Fig. Supp." (PMID 40671813, 2025). "As previous studies report, increased expression of P4HA2 was observed in various malignant tumors, including breast cancer, cervical cancer, and hepatocellular carcinoma." (PMID 41469036, 2025).
breast carcinoma (continued). "Specifically, P4HA2 regulates collagen deposition in breast cancer, and P4HA3 induces TGF‐β/Smad signaling activation to facilitate CRC cell growth and metastasis." (PMID 39764560, 2025). "In breast cancer, the level of P4HA2 mRNA is significantly greater than that in normal breast tissue, which is associated with a poor clinical prognosis." (PMID 40406250, 2025). "The role of hypoxia-driven signalling through the activation of P4HA2 in maintaining the partial or hybrid E/M phenotype in breast cancer was also recently examined." (PMID 38786043, 2024). "Over recent years, P4HA2 has been aberrantly overexpressed in various tumors, accelerating their malignant progression, including in B-cell lymphoma, breast cancer, and prostate cancer." (PMID 38951593, 2024). "Increased mRNA levels of P4HA1 and P4HA2 have been observed in human breast cancer facilitating collagen deposition and further promoting invasion and metastasis." (PMID 35202840, 2022). "The P4HA1 or P4HA2 knockdown also prevented breast cancer metastasis in mice by inhibiting collagen fiber development, thereby making it challenging for tumor cells to migrate into surrounding tissue." (PMID 36140753, 2022). "Inhibition of HIF-1α, P4HA1, or P4HA2 via short hairpin RNAs has been shown to decrease collagen deposition in breast cancer cells and fibroblasts in vitro." (PMID 36140753, 2022). "P4HA1 and P4HA2 expression has been reported to be altered in diverse tumor types, including oral cavity squamous cell carcinoma, prostate cancer, hepatoma, and breast cancer, and involved in tumor progression." (PMID 34168290, 2021). "Studies have shown that the expression of P4HA2 were upregulated in the oral cavity in squamous cell carcinoma, papillary thyroid cancer, and breast cancer." (PMID 29515771, 2018). "P4HA1 and P4HA2 in the cancer cells have been shown to be critical for breast cancer cell line collagen deposition, invasion and metastasization." (PMID 27809802, 2016). "The knockdown of either HIF-1α, P4HA1, or P4HA2 decreases tumor fibrosis and P4HA1 or P4HA2 knockdown completely abrogates the spontaneous metastasis of mammary fat pad-implanted human breast cancer cells to the lungs and lymph nodes of immunodeficient mice." (PMID 27706047, 2016). "Silencing P4HA2 or inhibiting its activity suppresses breast cancer progression by reducing tumor growth and metastasis, and this process is accompanied by reduced collagen deposition." (PMID 24383403, 2014). "P4HA2 mRNA levels were significantly upregulated in breast cancer compared to normal mammary tissue." (PMID 24383403, 2014). "In the present study, we show that P4HA2 is associated with expression of collagen I, III, and IV during breast cancer progression." (PMID 24383403, 2014). "Three-dimensional culture assay was used to analyze roles of P4HA2 in regulating malignant phenotypes of breast cancer cells." (PMID 24383403, 2014). "Taken together, these findings indicate that P4HA2 is a promising therapeutic target to inhibit ECM-dependent breast cancer progression." (PMID 24383403, 2014). "Increased P4HA2 expression has been detected in many solid tumors, including oral cavity squamous cell carcinoma, papillary thyroid cancer, and breast cancer, however, the function of P4HA2 in cancer progression largely remains to be determined." (PMID 24383403, 2014). "We also found that knockdown of P4HA2 inhibited mammary tumor growth and metastasis to lungs in xenograft models." (PMID 24383403, 2014). "P4HA2 is highly expressed in breast cancer and strongly correlates with poor prognosis." (PMID 41424847, 2026). "In TCGA-BRCA and GSE22820 breast cancer cohorts, P4HA2 expression positively correlated with ERBB2." (PMID 41424847, 2026). "P4HA2 is a potential therapeutic target that sensitizes breast cancer to radiotherapy." (PMID 41424847, 2026).
breast carcinoma (continued). "To determine whether P4HA2 upregulation is a conserved feature of dormancy, we examined its expression in multiple breast cancer dormancy models, including murine D2.0R and 4T07 and human HCC1954-LCC." (PMID 40671813, 2025). "Furthermore, studies have shown that P4HA2 promotes collagen deposition, which facilitates the proliferation, invasion, and metastasis of breast cancer cells." (PMID 38951593, 2024). "Additionally, in vivo experiments confirm this observation by proving that inhibiting HIF-1α, P4HA1, or P4HA2 in orthotopic tumors, developed via injection of human breast cancer cells into immunodeficient mice, decreases tissue stiffness and fibrosis." (PMID 36140753, 2022). "The same group of 7 breast cancer pathologists scored stromal P4HA2 expression." (PMID 35076865, 2021). "Elevated P4HA2 and 1 predict patient mortality in human breast cancers." (PMID 32500033, 2020). "In breast cancer, high P4HA1 and P4HA2 mRNA levels in primary tumors associate with poorer overall survival, and knockdown of either P4HA1 or P4HA2 may reduce collagen deposition and inhibit tumor invasion and metastasis in vivo." (PMID 32053263, 2020). "HIF-1 promotes extracellular matrix remodeling by inducing P4HA1 and P4HA2 in breast cancer." (PMID 31467922, 2019). "Furthermore, silencing P4HA2 or treatment with the P4HA inhibitor suppresses breast cancer progression by reducing tumor growth and a metastasis, which is accompanied by reduced collagen deposition, indicating its potential role as therapeutic target." (PMID 29515771, 2018). "Increased mRNA levels of P4HA2 correlate with poor prognosis in human breast cancer patients." (PMID 24383403, 2014). "First, using multiple radiation doses combined with P4HA2 knockdown, we found that breast cancer cells were significantly reduced under 4 Gy irradiation combined with P4HA2 knockdown, while cells nearly disappeared under 6 Gy irradiation combined with P4HA2 knockdown." (PMID 41424847, 2026). "Upon relevant literature search, we found that P4HA2 can promote the development of breast cancer and hepatocellular carcinoma by regulating collagen deposition, which may indirectly reveal the importance of P4HA2 in PTC; therefore, we selected P4HA2 for further in-depth study." (PMID 40379610, 2025). "Up-regulation of P4HA2 and PLOD2 by RASSF1C was also confirmed in lung and breast cancer cells in vivo using mouse models." (PMID 36826019, 2023). "Silencing of P4HA2 expression or treatment with a P4HA inhibitor significantly inhibited cell proliferation and suppressed aggressive phenotypes of breast cancer cells in 3D culture, accompanied by reduced deposition of collagen I and IV." (PMID 30410060, 2018). "Control and P4HA2-silenced breast cancer cells were injected into fat pad and tail vein of SCID mice to examine effect of P4HA2 on tumor growth and lung metastasis." (PMID 24383403, 2014). "Silencing P4HA2 expression or treatment with the P4HA inhibitor significantly inhibited cell proliferation and suppressed aggressive phenotypes of breast cancer cells in 3D culture, accompanied by reduced deposition of collagen I and IV." (PMID 24383403, 2014). "Further, RASSF1C up-regulation of P4HA2 and PLOD2 expression was confirmed in vivo in lung cancer tissue developed in an orthotopic mouse model and in breast subcutaneous tumor tissue derived from breast cancer cells overexpressing RASSF1C or RASSF1A." (PMID 36826019, 2023). "In sum, hypoxia directly regulates ECM composition via multiple enzymes and, as such, P4HA1, P4HA2, PLOD2, and LOX enzymes could be used as biomarkers in breast cancer progression." (PMID 36140753, 2022). "Increased mRNA levels of P4HA2 correlated with poor clinical outcome in breast cancer patients, which is independent of estrogen receptor status." (PMID 24383403, 2014).
breast carcinoma (continued). "In the GSE21653 breast cancer cohort, P4HA2 expression showed significant differences across tumor grades, with highest expression in G3, while in the TCGA-BRCA cohort, P4HA2 expression differed significantly across tumor stages, with highest expression in stage 4." (PMID 41424847, 2026). "Furthermore, neither ECM metagene-adjusted P4HA1 nor P4HA2 levels were higher in breast cancer than in normal tissue, which also contrasts what was found for P4HA3." (PMID 27809802, 2016). "However, expression and function of P4HA2 in breast cancer progression are not well investigated." (PMID 24383403, 2014).
cervical carcinoma (10 papers, 2020 to 2025). A carcinoma arising from either the exocervical squamous epithelium or the endocervical glandular epithelium. "Especially, we found that P4HA2 are markedly upregulated in cervical cancer tissues and upregulation of P4HA2 was associated with shorter overall survival (OS) and relapse-free survival (RFS)." (PMID 35111402, 2022). "The results suggest that P4HA2 is an independent prognostic factor and that high P4HA2 expression is associated with poorer survival in cervical cancer." (PMID 32226497, 2020). "Bioinformatics analysis was performed to investigate the underlying regulation mechanism of cervical cancer by P4HA2." (PMID 32226497, 2020). "Of note, multivariate analysis indicated that high expression levels of P4HA2 p=0.037, HR=1.825) were significantly associated with worse prognosis in cervical cancer patients independently of advanced FIGO stage (p=0.024, HR=2.307) and lymph node metastasis (p=0.000, HR=2.611)." (PMID 32226497, 2020). "Bioinformatics analysis indicated that EMT-related mechanisms underlined the functional role of P4HA2 in cervical cancer, we hypothesized that P4HA2 could promote cervical cancer cell invasion by regulating the EMT process." (PMID 32226497, 2020). "Studies have revealed that P4HA2 upregulates the expression of PD-L1 in cervical cancer tissues and is negatively correlated with CD8+ T cells, regulating antitumor immunity and serving as a prognostic marker for immunotherapy." (PMID 40406250, 2025). "Bioinformatics analysis exposed that P4HA2 was occupied with the regulatory mechanism of cervical cancer and was connected with shorter overall survival (OS) and recurrence‐free survival (RFS)." (PMID 40347062, 2025). "Accumulating evidence has confirmed that P4HA2 overexpression in multiple cancers, including lung adenocarcinoma, prostate cancer, glioma, and cervical cancer, has a correlation to patient prognosis." (PMID 38777998, 2024). "Recently, variation in P4HA2 expression has been observed in multiple cancers, e.g., oral cavity squamous cell carcinoma and cervical cancer, and has been correlated with the prognosis of patients." (PMID 36403427, 2022). "Upregulation of P4HA2 expression in cervical cancer was further confirmed by IHC staining on a tissue microarray (TMA) containing 90 cervical cancer tissues and 40 non-tumor adjacent tissues (ZZU TMA cohort)." (PMID 32226497, 2020). "To investigate the effect of P4HA2 knockdown on cervical cancer tumorigenesis, we established a SiHa cell line with stable knockdown of P4HA2." (PMID 32226497, 2020). "We also found that P4HA2 expression was significantly higher in multiple cervical cancer cells (CaSKi, HeLa, HT-3, C33A and SiHa) in comparison with that in normal cervical epithelium cell line HeCat." (PMID 32226497, 2020). "Functional analysis showed that P4HA2-silenced cervical cancer cells exhibited significantly suppressed proliferative and metastatic capacities." (PMID 32226497, 2020). "We found that the biological processes including “Focal adhesion” and “Adherens junction” were enhanced in cervical cancer patients with high P4HA2 expression." (PMID 32226497, 2020). "The GO enrichment analysis also showed enhanced activities including “focal adhesion”, “cell-substrate adherens junction”, “cadherin binding” and “cell adhesion molecule binding” in cervical cancer patients with high P4HA2 expression." (PMID 32226497, 2020). "In this study, we showed that P4HA2 is highly expressed in cervical cancer and that upregulation of P4HA2 is correlated with aggressive phenotypes and poor prognosis." (PMID 32226497, 2020). "In the current study, we demonstrated collagen P4HA2 was upregulated in cervical cancer and P4HA2 overexpression correlated with poor prognosis of cervical cancer patients." (PMID 32226497, 2020). "P4HA2 was silenced to evaluate its function on cervical cancer progression both in vitro and in vivo." (PMID 32226497, 2020).